INS (insulin)
Diseases named in the same sentence as INS in open-access papers (continued):
Sharing a sentence is not in itself a finding about the gene and the disease.
Insulin resistance (continued). "In addition, the fasting insulin level and HOMA-IR index score were significantly reduced with combined nutraceutical administration, suggesting reduced insulin resistance." (PMID 31881654, 2019). "In contrast to glucose, fructose does not stimulate insulin secretion and chronic exposure facilitates insulin resistance." (PMID 31010049, 2019). "Serum insulin is also elevated after O3 suggesting insulin resistance rather than impaired insulin release and experiments using euglycemic clamps verify insulin resistance." (PMID 31867021, 2019). "Similar effect of insulin resistance was observed for both saturated and monounsaturated fatty acids, as no stimulation of glucose uptake by insulin was observed or such stimulation was negligible." (PMID 31883537, 2019). "Samples used in the study were randomly collected for this reason it was not possible to determine HOMA-IR or other indices of insulin resistance derived from fasting glucose and insulin levels." (PMID 31214116, 2019). "Taking all this into account, the cross-talk between FSH and insulin might involve IRS1, especially in case of insulin resistance, but this needs to be elucidated." (PMID 31174276, 2019). "Neither did we find a correlation between markers of insulin resistance and metabolic syndrome and insulin promotor DNA methylation status." (PMID 30953560, 2019). "Another limitation may be the use of insulin levels and HOMA index as surrogate markers of insulin resistance, which differs from the gold standard method, the hyperinsulinemic euglycemic clamp." (PMID 31064394, 2019). "In addition, insulin levels are often elevated in T2DM and accompanied with insulin resistance, while they are lowered in T1DM (although insulin resistance can also appear in T1DM)." (PMID 31888259, 2019). "Meanwhile, insulin stimulation was reduced, and no longer significant, after MI treatment (p = 0.056 basal vs. insulin), indicating an induction of insulin resistance." (PMID 32038288, 2019). "In addition, in the TNF-α-induced insulin resistant cell model, we also found naringenin restored TNF-α-induced insulin resistance." (PMID 31591391, 2019). "During pregnancy, hypothalamic PTEN is less inactivated by low phosphorylation than during non-pregnancy periods, thereby inducing hypothalamic insulin resistance, which protects animals from insulin-induced anorexia." (PMID 30875909, 2019). "Animal models of T2D have also indicated a deleterious role of iNOS related to insulin resistance, however skeletal muscle iNOS expression was reported to be similar between insulin sensitive non-obese compared with obese insulin resistance adults." (PMID 31382355, 2019). "Insulin resistance: For 90% to 95% of patients, T2DM is caused by a progressive deficiency in insulin secretion, leading to a lack of relative insulin secretion in insulin-resistant patients." (PMID 31835423, 2019). "FBG, TG, fasting insulin, and HOMA-IR levels increased in rats fed on low or high glycemic index diet compared to rats fed on a normal diet (P < 0.01), indicating the successful establishment of the DM model of rats with insulin resistance." (PMID 31093316, 2019). "We did not observe significant differences in maternal insulin levels at late gestation, change from baseline, or cord blood C-peptide, which is examined as markers of neonatal insulin resistance." (PMID 30998227, 2019). "In the tightly controlled glucose metabolism, chemerin was shown to regulate glucose-induced insulin release and insulin-stimulated glucose uptake in skeletal muscle, but did not contribute to peripheral insulin resistance in general." (PMID 31370263, 2019). "After 12 weeks, neither group differed from one another in measurements of insulin sensitivity (HOMA of insulin resistance (HOMA-IR) and Matsuda Index), fasting glucose and insulin, or hemoglobin A1C." (PMID 31547352, 2019).
Insulin resistance (continued). "In both FHS and MCDS, ΔBMI and MRS are generally negatively correlated with variables that assessed insulin resistance (i.e. fasting/2-hour glucose and insulin, and HOMA-IR) and positively correlated with those that marked insulin sensitivity (i.e. Matsuda ISI and QUICKI)." (PMID 31560688, 2019). "Type 2 diabetes is characterized by insulin resistance, whereas Type 1 diabetes is often genetic and occurs when the pancreas produces little or no insulin." (PMID 31775750, 2019). "Biochemical measures were fasting glucose, insulin and lipids, oral glucose tolerance testing (OGTT), hemoglobin A1c, and insulin resistance assessed with the homeostatic model (HOMA-IR) were determined in a consecutive cohort of 798 adult psychiatric inpatients receiving antipsychotics." (PMID 31513598, 2019). "Glucose intolerance and insulin resistance are common complications in CKD and elevated insulin level could have a hypertrophic effect on the heart." (PMID 30718600, 2019). "Our results indicate that female mice are protected from age‐related obesity and insulin resistance, and that unlike diet‐induced obesity, MitoQ does not reduce adiposity or improve insulin action in AG mice." (PMID 30706674, 2019). "The negative relationship between RET4 and insulin sensitivity was further verified in mice that developed insulin resistance upon overexpression of RET4, whereas insulin action was improved upon RET4 depletion." (PMID 31623319, 2019). "When insulin resistance occurs, insulin is incapable of regulating HGP in the liver and fails to phosphorylate GSK3, which can be a surrogate marker of the development of an insulin-resistant state." (PMID 30616503, 2019). "Recent invitro studies have revealed differential insulin signaling inhuman luteinized granulosa cells of PCOS patients withand without insulin resistance." (PMID 30507086, 2019). "Although pioglitazone is known as an insulin sensitizer, it also has a potent modulator of cell growth and apoptosis irrespective of insulin resistance." (PMID 31472696, 2019). "A study conducted on obese rats with insulin resistance, showed that the neutralization of TNFα with a soluble fusion protein, IgG-tumor necrosis factor receptor (TNFR), increases insulin sensitivity and restores plasma insulin values close to normal levels." (PMID 31344895, 2019). "Chronic activation of the mTOR/S6K1 pathway by insulin, TNF-α and amino acids promote insulin resistance in obese mice and primary cultures of skeletal muscle cells from patients with type 2 diabetes through increased IRS1 serine phosphorylation and degradation." (PMID 31130916, 2019). "Moreover, impaired intracellular insulin signaling pathways and increased HOMA-IR indexes are accepted markers of insulin resistance, which leads to abnormal blood lipid profiles and Very Low Density Lipoprotein 1 (VLDL1) increases." (PMID 30881473, 2019). "This suggests that C18-ceramides are not a main lipid actor for the development of insulin resistance in these animals or that the remaining muscle C18-ceramide content is enough to inhibit muscle insulin sensitivity." (PMID 30678043, 2019). "In terms of insulin resistance parameters, we found a slight decrease in plasma glucose and insulin levels after treatment, though these changes were not statistically significant." (PMID 31690730, 2019). "Previously, we reported that carrageenan induced glucose intolerance and insulin resistance by two distinct mechanisms, including an increase in phospho(Ser307/312)-IRS1, a negative regulator of insulin signaling, and decline in phospho(Tyr)-IRS1, a positive regulator of insulin signaling." (PMID 31179345, 2019). "Defects in the insulin-signal receiving cell are akin to insulin resistance present in type II patients, where there is no lack of insulin producing cells." (PMID 30805360, 2019).
Insulin resistance (continued). "Given the presence of insulin resistance in a subset of DM1 patients, patient stratification will be important in future studies, especially clinical therapeutic trials as insulin-modifying therapies may be relevant to some DM1 patients but not all." (PMID 31849810, 2019). "Likewise, plasma insulin levels and the HOMA index of insulin resistance were higher in ZDF rats in comparison to ZL rats (p < 0.01), but both metabolic parameters were not significantly improved by the treatment with α-lipoic acid." (PMID 31888243, 2019). "Experimental evidence has shown that oxidative stress and increase in pro-inflammatory cytokines is closely related to insulin resistance, through their negative activity on insulin signaling pathways and glucose transport into the cell." (PMID 30976328, 2019). "In some insulin-resistant patients, protein tyrosine phosphatase 1B (PTP1B) interacted with insulin receptor and induced insulin receptor dephosphorylation, resulting in inactivation of insulin signaling pathway." (PMID 31396083, 2019). "Despite our efforts to scrutinize insulin resistance, the lack of plasma insulin levels in this study prevents any definitive conclusions with regard to insulin resistance." (PMID 31485454, 2019). "Insulin resistance or lack of insulin signaling in adipose tissue of diabetic individuals impairs the inhibition of triglyceride lipolysis by insulin, leading to high levels of circulating fatty acids." (PMID 31212580, 2019). "Insulin resistance did not change significantly over time in this cohort, and, similarly to the Lean group, ObSen maintained their superior insulin sensitivity relative to ObRes at follow-up." (PMID 31071971, 2019). "Skeletal muscle insulin resistance has not been directly assessed in humans with AS160 deficiency, but lower glucose uptake by most insulin-stimulated skeletal muscles has been consistently found in AS160-KO rodents compared to WT controls." (PMID 31034517, 2019). "Diabetes is a chronic metabolic disease characterized by high blood glucose, mainly the result of a lack of insulin production and/or insulin resistance (IR)." (PMID 30886061, 2019). "However, there was no significant change in whole-body insulin sensitivity, including the homeostasis model assessment-estimated insulin resistance (HOMA-IR) and the glucose-insulin (G-I) index." (PMID 31286941, 2019). "Insulin resistance occurs at a tissue-specific level; however, no study has simultaneously compared whole body, skeletal muscle, hepatic and adipose tissue insulin sensitivity between black and white men." (PMID 30729259, 2019). "Our results have clearly demonstrated that vitamin E in the form of TRF significantly downregulates ROS production after the induction of chronic insulin resistance, even though it did not exert any significant effect on the insulin signalling molecules." (PMID 31635074, 2019). "With damaged β cells of pancreas due to STZ injection in mice, hyperglycaemia and low insulin level, namely, insulin resistance, were observed in non-MBBP feed group (model group)." (PMID 30800168, 2019). "Independent of insulin resistance, the levels of insulin and glucagon were mainly at fasting levels." (PMID 30908518, 2019). "Study limitations include a lack of blood levels of glucose and insulin and a lack of indicators of insulin resistance (especially in the brain) and β-cell function for more in-depth analyses." (PMID 31085804, 2019). "Furthermore, index of insulin resistance was calculated using the obtained concentration of BGL and insulin level accordingly." (PMID 32158428, 2019). "Thus, regardless of sex, individuals with higher ALT concentrations had higher HOMA-IR and glucose, insulin, and triglyceride concentrations and lower HDL-C concentration—all known biomarkers of insulin resistance." (PMID 30987010, 2019).
Insulin resistance (continued). "However, another study reported that overexpression of miR-181a-5p in adipocytes upregulated insulin-stimulated AKT activation and reduced TNFα-induced insulin resistance." (PMID 30717412, 2019). "Similarly, glucose homeostasis was not affected by the eight weeks of the HPD administration since both glucose, insulin concentrations, and HOMA-IR (homeostatic model assessment of insulin resistance) were similar to the CON animals." (PMID 30925663, 2019). "Moreover, HFD worsened the insulin resistance slightly, while HFD+SC06 marginally improved the insulin sensitivity (p = 0.058)." (PMID 31191487, 2019). "Cocoa treatment did not affect glucose, insulin, homeostasis model assessment for insulin resistance (HOMA-IR), triglycerides, total cholesterol, low density lipoprotein-cholesterol, high density lipoprotein-cholesterol, and BP." (PMID 30781485, 2019). "Higher rates of mitochondrial ROS production by SFAs are reported to be involved in the activation of the NLRP3 inflammasome and weakening of insulin sensitivity, thereby supporting the existence of the relationship between HFD, inflammation, and insulin resistance." (PMID 31817726, 2019). "Epidemiologic studies have focused on simple measurements of insulin sensitivity based on glucose and insulin fasting plasma samples, such as the homeostasis model assessment insulin-sensitivity (HOMA-S) index, which is the inverse of the commonly used HOMA-insulin resistance (HOMA-IR) index." (PMID 31208038, 2019). "Recent studies have confirmed that short-term exposure to high glucose significantly decreased the binding affinity of insulin to caveolin-1 and INSR in mature adipocytes, which might contribute to the development of insulin resistance in early T2DM." (PMID 31658625, 2019). "T2DM is a serious chronic metabolic disease triggered by impaired insulin signal pathways and systemic insulin resistance and the lack of response to insulin target cells such as hepatocytes, skeletal muscle cells, and adipocytes." (PMID 31828133, 2019). "In turn, dysregulation of serum glucose upon CaBP-9k ablation was the result of the dysregulation of insulin production or secretion and not insulin resistance." (PMID 31731478, 2019). "Overall, ITF supplementation could significantly reduce concentrations of fasting blood glucose (FBG), glycosylated hemoglobin (HbA1c), fasting insulin (FINS) and homeostasis model assessment-insulin resistance (HOMA-IR)." (PMID 31805963, 2019). "In addition, the insulin signaling pathway (IRS-1/AKT/FOXO1) was activated, further demonstrating that Nifu mitigates PA-induced insulin resistance by activating insulin signaling." (PMID 35540668, 2019). "Indeed, half of our DM patients were overweight, 39% were glucose intolerant or diabetic, and 25% were receiving statins; this confirms the frequency of insulin resistance confirmed by higher 120-min OGTT glucose and insulin levels." (PMID 30760283, 2019). "In the long-term, insulin resistance is observed when insulin does not effectively regulate plasma glucose and FFA." (PMID 31499737, 2019). "Along with insulin resistance, beta cell dysfunction is a major component of T2D pathology, and clinical onset of T2D does not occur until beta cells fail to secrete sufficient insulin to maintain normoglycemia in the face of insulin resistance." (PMID 31921662, 2019). "During insulin resistance, the phosphatidylinositide-3-kinase (PI3K) signalling pathway that controls the metabolic effects of insulin activation is impaired, whilst activation of the proinflammatory, mitogenic extracellular signal-regulated kinase 1/2 (ERK1/2) pathway is enhanced." (PMID 30719343, 2019). "For instance, it is conceivable that pancreatic beta cells are less able to compensate for insulin resistance in CKD (and other muscle-wasting states) than in obesity, perhaps because of harmful effects of uraemic retention molecules on the insulin secretion from pancreatic beta cells." (PMID 31195596, 2019).
Insulin resistance (continued). "We also revealed that GDM women without increases in insulin resistance had impaired insulin secretion at midpregnancy." (PMID 31275653, 2019). "As known, C-peptide levels depend only on insulin production, are not affected by insulin replacement and are directly related to insulin resistance which, in turn, plays a pivotal role in the pathogenesis of MetS." (PMID 31673296, 2019). "Previous studies have shown that ethanol can in part induce hepatic insulin resistance through the inhibition the PI3K/AKT pathway by decreasing IR density, inhibiting the binding affinity between insulin and its receptor, and decreasing receptor phosphorylation." (PMID 31555134, 2019). "Insulin resistance is the condition in which the cells of the muscles, fat, and liver do not respond well to insulin and do not easily take up glucose from blood." (PMID 30678306, 2019). "Since hepatic steatosis is recognized as a primary contributor to systemic insulin resistance, CLE may improve insulin sensitivity by suppressing the development of hepatic steatosis." (PMID 31208033, 2019). "An in vivo and in vitro study demonstrated that a high serum UA level could directly induce insulin resistance by inhibiting IRS1 and Akt insulin signaling." (PMID 30944567, 2019). "Despite elevated serum glucose levels, the PUFA-enriched HF diet did not result in insulin resistance or an increase in serum insulin, as observed in animals in the SFA-rich HF diet group." (PMID 31771244, 2019). "Another particularly interesting agent in the field of DCM therapy is pioglitazone, an insulin-sensitizer from the thiazolidinedione (TZD) class of nuclear peroxisome proliferator-activated receptor γ-agonists, which decreases insulin resistance in the liver and peripheral tissues." (PMID 30736394, 2019). "Vamorolone did not induce hyperinsulinemia as a precursor of insulin resistance, which is consistent with recent human Phase 1 data where no changes in blood insulin and glucose levels were observed up through the highest dose (20 mg/kg/d) tested." (PMID 30745312, 2019). "Inflammation and insulin resistance are closely related, and inflammatory cytokines such as TNF-α, IL-6, IL-1, and IL-8 may inhibit insulin signaling via multiple mechanisms." (PMID 31118902, 2019). "For example, vitamin D substitution in obese or insulin-resistant subjects leads to the amelioration of insulin resistance without affecting insulin secretion." (PMID 30609782, 2019). "Statin dose-dependently induces ß cell damage and insulin resistance in the smooth muscle cells, reduces glucose transporter 4 (GLUT4) expression which is involved in glucose uptake in the peripheral cells, and decreases insulin signaling." (PMID 31044020, 2019). "Furthermore, in conditions characterized by insulin resistance, such as obesity and T2DM, lymphocytes have an impaired response to insulin." (PMID 31885787, 2019). "In the etiology of T2DM, BCF basically determines whether a person with a certain degree of insulin resistance develops T2DM, as β-cells are able to compensatorily increase insulin secretion." (PMID 29525890, 2019). "Moreover, insulin resistance index (IRI) and HOMA-insulin secretion B cell (HOMA-B) were found to be higher and insulin sensitivity index (ISI) to be lower in patients compared with controls." (PMID 31031703, 2019). "The significant correlation between circulating levels of TIMP-1 to insulin, and HOMA2-IR, might nevertheless, reflect that remodeling in AT is related to insulin resistance and MetS." (PMID 31890043, 2019).